RN7SL687P (RNA, 7SL, cytoplasmic 687, pseudogene)
Gene: Miscellaneous RNA gene on chromosome X (153,666,226 to 153,666,510, forward strand). Ensembl gene ENSG00000244335.
Homologues: Orthologues: chimpanzee Metazoa_SRP (97% identical), macaque Metazoa_SRP (93% identical), guinea pig Metazoa_SRP (58% identical). Paralogues in human: RN7SL1 (84% identical), RN7SL2 (84% identical), RN7SL3 (83% identical), RN7SL664P (82% identical), RN7SL126P (81% identical), Metazoa_SRP (80% identical), RN7SL679P (80% identical), RN7SL709P (80% identical), RN7SL627P (80% identical), RN7SL43P (80% identical), RN7SL492P (80% identical), RN7SL786P (80% identical), and 701 more.